IL4 (interleukin 4)
Diseases named in the same sentence as IL4 in open-access papers (continued):
Sharing a sentence is not in itself a finding about the gene and the disease.
tumor (continued). "Tumor cells can influence which phenotype a macrophage adopts by secreting IL-4 promoting the M2 phenotype, which has demonstrated the ability to remodel the surrounding tumor stroma, promoting tumor invasion." (PMID 37173966, 2023). "qPCR results indicated that the effect of tumor-derived exosomes is very similar to that of IL-4, which efficiently increased the immunosuppressive factors, including TGF-β1 and IL-10." (PMID 36902024, 2023). "In in vitro study, we treated the THP-1 cells with phorbol 12-myristate 13-acetate (PMA) to differentiate into macrophages and co-cultured these with tumor-derived exosomes interferon-γ (IFN-γ)/lipopolysaccharide (LPS) or IL-4." (PMID 36902024, 2023). "These cells have lost their normal functions after being recruited and co-opted by the tumor through exposure to cytokines produced by the tumor cells, such as IL-4, IL-10, transforming-growth factor-β1 (TGF-β1), and prostaglandin E2 (PGE2)." (PMID 37082492, 2023). "This agrees with single‐cell transcriptome analyses that have detected expression of genes up‐regulated by IL4 and IFNγ in some tumor‐derived macrophages." (PMID 37199012, 2023). "IFN-Y induces polarization of TAMs, TNF-α, and lipopolysaccharide (LPS) into the M1 (classically activated/anti-tumor) macrophage phenotype and IL-4, IL-190, TGFβ1, and PGE2, into the M2 (alternatively activated/pro-tumor) macrophage phenotype." (PMID 37637998, 2023). "In ovarian cancer cell membranes, cholesterol efflux drives TAM reprogramming and tumor progression by inducing an IL4-mediated Th2-like environment." (PMID 38035101, 2023). "In contrast, tumor-derived soluble factors M-CSF, IL-6, IL-1β, IL-4, IL-10, CCL2 initiate the immunosuppressive pathways that commit immature myeloid cells to become MDSCs and further promote the differentiation towards M-MDSC." (PMID 38304256, 2023). "Other studies have achieved similar results by injecting IL-4 into the tumor-draining lymph node or directly into the tumor." (PMID 36980536, 2023). "In the tumor region, the recruited monocyte is easily differentiated into M2-type TAMs due to the abundance of Th2 cytokines (IL-4, IL-10, IL-13), limiting antigen presentation and promoting immunosuppression." (PMID 38258072, 2023). "In the LN ecosystem, the interaction between MCL tumor cells and T cells through CD40L and IL-4 is fundamental to promote tumor proliferation and viability." (PMID 37031299, 2023). "β2AR signaling can also polarize macrophages from M1 to M2 type, thereby enhancing anti-inflammatory cytokines like IL-10, IL-4 & IL-13, and decreasing pro-inflammatory cytokines like INFγ, TNFα, IL1β, CCL2, CCL3 and CCL4 to cause tumor progression." (PMID 37006295, 2023). "Tumour cells express elevated levels of IL-4R, and IL-4 signaling reduces cancer cell apoptosis through the upregulation of anti-apoptotic genes while also directly promoting tumour cell proliferation." (PMID 37455828, 2023). "This indirect mechanism enhances the lack of proinflammatory cytokines production and decrease capacity to activate effector T cells probably via IL‐4 production, and thus contribute to the immunosuppressive tumour microenvironment." (PMID 38117000, 2023). "Implantation of a mixture of FaDu cells and IL4-induced macrophages promoted tumor growth and proliferation, which were abrogated by the knockdown of LINC01569 in macrophages." (PMID 37325064, 2023). "In contrast, M2 macrophages are activated by Th2 cytokines interleukin-4/13 (IL-4/IL-13), and play roles in fibrosis, anti-inflammatory response, and tumor progression." (PMID 37720221, 2023). "These cells can be converted into TAMs through soluble factors present in the tumor microenvironment such as IL-6, interleukin-10 (IL-10), interleukin-4 (IL-4), interleukin-13 (IL-13) and TGF-β57-60." (PMID 37215442, 2023). "IL-4 signaling and cholesterol efflux pathways contribute to the immune suppression of TAMs and tumor progression in vivo." (PMID 37740232, 2023).
tumor (continued). "In exploring the immune cells involved in human pancreatic cancer (PC), IL4-expressing basophils were identified in the tumor-draining lymph nodes (TDLNs)." (PMID 37205111, 2023). "The authors found out that, due to iNOS activity, the classic Th2 response was completely (IL‐4 and IL-13) or markedly (IL‐5, IL‐6, IL‐9, and IL-10) inhibited after tumor irradiation." (PMID 37347290, 2023). "This process was dependent on recruitment of eosinophils to the tumor site and the activation of the IL-4/STAT6 signaling pathway." (PMID 36980536, 2023). "The presence of interleukin-4 (IL-4) in tumor cells is known to modulate cell survival, proliferation, and metastasis." (PMID 37345061, 2023). "In TAM, in colon cancer cells, PKN2-inducible DUSP6 leads to the suppression of tumor-associated M2 macrophage polarization and tumor growth, through the inhibition of the ERK1/2, IL-4, and IL-10 cascade." (PMID 38139370, 2023). "In contrast, M2 macrophages support tumor growth and progression through hypoxia and the secretion of cytokines (e.g. IL-4)." (PMID 37056757, 2023). "In pancreatic cancer models, IL-4 induces substantial histoproteinase activity in TAMs and mediates tumour growth, angiogenesis and invasion in vivo." (PMID 38143746, 2023). "In B7H4 positive tumours, a cluster consisting of IL-5, IL-4, VEGFA, M-CSF, IFN-γ, IL-Ra, IL-8, and IL-1β was chosen for further analysis." (PMID 36980202, 2023). "This can be explained by the ability of tumor cells to hijack M2a cells to support their growth via the IL-4/STAT6-mediated pathway." (PMID 37108657, 2023). "In fact, Budiani and colleagues reported an increase in IL‐4 production both at the tumour level and in the sera of NPC patients compared to controls." (PMID 38117000, 2023). "The expression levels of IL4 were significantly higher while TNFA was slightly reduced in tumor tissues of AOM/DSS mice treated with AAT than in AOM/DSS mice." (PMID 37532996, 2023). "In particular, the radiation-regulated miR-340/429/IL-4/β-catenin/Stat6 signaling axis effectively enhanced tumor progression and metastasis of human carcinomas." (PMID 36769373, 2023). "Albeit later, Tc2 effector subpopulation was also demonstrated to be localized in the tumor site along with Th2 with higher IL-4 and IL-10 production which seemed to be correlated to tumor growth and metastasis in untreated mice." (PMID 37835465, 2023). "They generated multicellular tumour spheroids (MCTS) using various tumour cell lines and cultured monocytes in the presence of granulocyte macrophage colony-stimulating factor (GM-CSF) and IL-4." (PMID 36761981, 2023). "Since IL-4 and IL-13 are anti-inflammatory cytokines, their role in cancer is primarily related to their ability to modulate anti-tumor immune responses." (PMID 37760903, 2023). "In this context, the levels of GM‐CSF, TNF‐α, IFN‐γ, IL‐1β, IL‐2, IL‐4, IL‐6, IL‐10, and IL‐13 in the peripheral blood of H22 tumor‐bearing mice were detected." (PMID 36043445, 2023). "In our study, leptin level was higher while IL-4 level was lower in the tumor animals compared to other animals." (PMID 36834959, 2023). "Tumours have been reported to release growth factors such as M-CSF, and cytokines including IL4 and IL10, which initiate differentiation of macrophages into tumour-associated macrophages (TAMs)." (PMID 37893161, 2023). "Cytokine profiling showed elevated IL-4-producing Th2 cells earlier than IFN-γ-producing Th1 cells, which remained noticeably higher and was linked with tumor growth and metastases." (PMID 37835465, 2023). "Th2 cells have been reported to promote tumor progression by releasing inflammatory factors such as IL-4/IL-13, and by promoting M2 macrophage polarization and activation of myeloid-derived suppressor cells (MDSCs)." (PMID 37744268, 2023).
tumor (continued). "Early studies of IL-4 soon after its discovery found that overexpression of IL-4 by tumour cell lines through genetic approaches led to tumour rejection after in vivo implantation, consistent with an anti-tumoural role." (PMID 37455828, 2023). "TAMs are typically M2-like and polarized by immunosuppressive cytokines such as IL-4, IL-13, or IL-10 in the tumor microenvironment." (PMID 37175092, 2023). "Th2 cells are also important tumor-promoting cells that can promote the M2 polarization of macrophage by secreting IL4 and IL13 cytokines." (PMID 37610668, 2023). "On the other side of the coin, M2 macrophage functions through secreting IL-8 and IL-4, to form an immune-suppressive microenvironment to facilitate tumor development." (PMID 37040507, 2023). "Nevertheless, given their overarching effects on tumour immunity, acting upstream of the main effector type 2 cytokines IL-4, IL-5, IL-9, and IL-13 and T cells, the prospect of therapeutically targeting these cytokines is promising." (PMID 37455828, 2023). "To examine the anti-tumor impact of increased IL-4 production, we blocked IL-4 intratumorally using an IL-4 blocking antibody." (PMID 38203396, 2023). "Alternatively, these same combinations simultaneously upregulated IL-4, which activates pro-tumour M2 macrophages, highlighting the complex interplay between immunosuppressive and immunostimulatory processes." (PMID 37373179, 2023). "Through IL‐4 stimulation, they have been involved in interactions with Treg cells that infiltrate tumours and in the suppression of tumour immunity mediated by CD8 T cell." (PMID 37784253, 2023). "‐Blocking IL‐4 signaling by anti‐IL‐4R delayed tumor growth.‐Prevention of cholesterol efflux by genetic deletion of ABC membrane cholesterol efflux transporters delayed tumor growth." (PMID 36658699, 2023). "It is well-established that IL-4 is a tumor-promoting molecule, as many tumor cells express high levels of the IL-4 receptor." (PMID 37444608, 2023). "TAMs and other tumor-promoting cells in TME can also facilitate the polarization of monocytes toward TAMs by releasing IL-4, IL-10, IL-13, and TGF-β." (PMID 37221555, 2023). "IL-4 has conflicting roles in cancer—some studies show that it is a strong anti-tumor therapy agent while others demonstrate that it promotes tumor progression." (PMID 36814782, 2023). "We investigated the expression of IFN-γ, IL-2, IL-4 and IL-12 inflammatory cytokines by q-PCR within the tumor tissues." (PMID 37894298, 2023). "The elevated tumor secretion of IL-4 was found to play a role in the modification of cancer cell differentiation and growth and resistance to apoptosis." (PMID 36012769, 2022). "On the contrary, the M2-like macrophages are activated by the type 2 T helper cell (Th2) cytokines such as IL-4, IL-10 and IL-13, and exhibit promoting tumor capacity." (PMID 36518756, 2022). "On the contrary, Th2 cells are associated with anti-inflammatory response, immunoglobulin E, and eosinophilic responses by IL-4, IL-5, and IL-13 secretion and the activation of TAMS and, therefore, are associated with tumor progression." (PMID 36142615, 2022). "Among the immunosuppressive cytokines, IL-4, TGFβ and IL-10 are the most representative at the tumor site, contributing to CAR-T cell dysfunction." (PMID 39086964, 2022). "IL-4 and IL-31 mediate the activation of eosinophils and mast cells and indirectly activate B lymphocytes to produce IgE, contributing to skin itching and allergic inflammation." (PMID 35805534, 2022). "On the contrary there was an increase in the Th2 mediators IL-4, IL-6, IL-27, soluble chemokine ligands and pro-inflammatory mediators responsible for promoting pro-tumor immune cells; MCP-1, and IL-16." (PMID 35154142, 2022). "M2 macrophages are derived from M1 activation by factors such as IL-4 and IL-13 and have the potential to suppress immune responses, promote angiogenesis, tissue repair and promote tumor growth." (PMID 35546682, 2022).
tumor (continued). "Interferon gamma and LPS inhibited macrophage-dependent tumor cell extravasation while the Th2 cytokine interleukin-4 (IL4) enhanced this process." (PMID 36077870, 2022). "Monocytes from PBMCs were cultured in a medium with GM-CSF and IL-4, followed by pulsing with hypochlorous acid (HOCl)-oxidized whole tumor lysate and maturation with LPS and IFNγ." (PMID 36011029, 2022). "IL-4 is highly expressed in the tumor microenvironment, and studies have shown that its neutralization can improve therapeutic response." (PMID 36143043, 2022). "As a major activator of TAM phenotypes in tumor microenvironment, IL-4 supplied by either T cells or tumor cells can act on TAMs to up-regulate cathepsin enzyme activity in TAMs and augment the EGF/CSF-1 paracrine loop between TAMs and tumor cells." (PMID 35996149, 2022). "For CCL5-deficiency MDSC-DCs, we constructed tumor models developed in CCL5-knockout mice and induced MDSCs via GM-CSF and IL-4 into CCL5−/−MDSC-DCs." (PMID 35707772, 2022). "Cytokines produced by Th2, particularly IL-4 and IL-13, can not only reduce anti-tumor immune responses, but also can directly accelerate tumor growth induced by KRAS transformed cells." (PMID 36408139, 2022). "Th1 activate anti-tumor immune reaction by secreting IL-2 and IFN-γ whereas Th2 suppress anti-tumor immune reaction by secreting IL-4, suppressing NK cells, and lowering tumor antigen expression." (PMID 36293435, 2022). "It has been observed that IL-4 in combination with IL-13 induces macrophages to support tumor survival by creating an immunosuppressive environment and enhancing tissue repair." (PMID 35884700, 2022). "Interleukin-4 (IL-4), known as Th2-related cytokines serving as tumor supportive microenvironments, increased in MB49 implanted mice, but significantly decreased in PLAG and aPD-L1 treated mice." (PMID 35787261, 2022). "For the first time, the correlation of salivary levels of TNF-α, IL-1β, and IL-6 with HER2 status, MCP-1, IL-1β, IL-2, and IL-4 with the hormonal status of the tumor was shown." (PMID 36286034, 2022). "Significant increase in IL4 (control/tumor tissue) (p=0.025) and TNF-α (control/tumor tissue) (p=0.012) levels was revealed." (PMID 35237320, 2022). "It has been acknowledged that Th2 cells induce macrophages polarized to pro-tumor M2 phenotype through the secretion of IL-4 and IL-13." (PMID 36564797, 2022). "The lowest tissue levels of IL-4 were observed in the tumor-bearing mice receiving S. cerevisiae (109 cells/mL)." (PMID 35974992, 2022). "M1 macrophages (CD86+ and CD80+) release pro-inflammatory cytokines (e.g., IL-6, IL-12, TNF-α) to play an anti-tumor role, while M2 macrophages (CD206+) release pro-tumor cytokines (e.g., IL-4, IL-10, IL-13) to promote tumor progression and metastasis." (PMID 35432300, 2022). "Upregulation of IL-4, IL-5, and IL-6 was detected in the healthy hemisphere in the first days after tumor resection, which later reverted to basal level, indicating a transient in-brain inflammatory response to the surgical intervention." (PMID 35884700, 2022). "Monocyte from PBMCs were cultured in a medium with GM-CSF and IL-4, followed by pulsing with HOCl-oxidized whole tumor lysate and maturation with LPS and IFNγ." (PMID 36011029, 2022). "The exogeneous FA consumption and de novo FA synthesis contributed to the cancer stemness of the isolated HCC clones, whereas the cytokine receptor signaling, including receptors for IL-4 and IL-13, enhanced tumor growth." (PMID 35721518, 2022). "Larger tumor size and/or LN involvement were associated with lower frequencies of CD4+TNF-α+, CD8+IFN-γ+ and CD8+IFN-γ+TNF-α+ but higher frequency of CD4+IL-4+ T cells." (PMID 36376825, 2022). "Tumor derived factors, such as M-CSF and IL-4, promote the peritoneal residential macrophages self-proliferation or differentiation from monocytes." (PMID 36035994, 2022).
tumor (continued). "In this study, the exosomes secreted by PMA- and IL-4-differentiated TAMs were found to significantly increase CCA tumor progression as determined by using both in vivo and in vitro parameters." (PMID 35091535, 2022). "We also report that presence of IgG4 + B cells correlates with tumor expression of IL-10 and trends with expression of IL-4 by tumors." (PMID 35255925, 2022). "In a mouse ovarian metastatic model, tumor cells promote membrane-cholesterol efflux and depletion of lipid rafts from macrophages which promotes IL-4-mediated reprogramming but inhibits IFNγ-induced gene expression to accelerate tumor progression." (PMID 36035994, 2022). "Monocytes from PBMCs were cultured in a medium with GM-CSF and IL-4, followed by pulsing with whole tumor lysate and stimulation with Poly I:C." (PMID 36011029, 2022). "Upon addition of a tumor-conditioned medium (TCM) to an anti-tumor cytokine cocktail (IL-4 and IL-10) in addition to M-CSF, TAMs can be generated." (PMID 36358879, 2022). "When the TME becomes more pro-tumor, IL4, IL13, or IL10, produced by Th2 or Treg cells, promote M2 or M2-like phenotype for TAM, displaying protumor functions." (PMID 35163420, 2022). "Together, these data suggest that IL4 signaling is important for the in vivo control of tumor progression by targeting both tumor cells and immune cells in the TME." (PMID 36077870, 2022). "On the other hand, it was demonstrated that along with the metastasis of the tumor cells into the draining LNs and progression of the disease to advanced stages, the frequencies of CD8+ T cells expressing Tc2-associated cytokines (IL-4, IL-10) increased." (PMID 36376825, 2022). "The secreted IL-33 recruited and activated Th2 and innate lymphoid cells 2 (ILC2) in the tumor microenvironment (TME), which stimulated tumor growth by secreting pro-tumor cytokines, such as IL-4, IL-5, and IL-13." (PMID 35910636, 2022). "In their study, the DCs (culture of monocytes with GM-CSF and IL-4) were transfected with total tumor RNA or normal RNA." (PMID 35619702, 2022). "Injection of IL-4 enhanced tumour clearance and resulted in an increase in the infiltration of eosinophils, macrophages, neutrophils, and some lymphocytes." (PMID 36261459, 2022). "Several immunosuppressive cytokines, including IL-10 and IL-4, are secreted from tumor cells and known to polarize TAMs to a pro-tumor phenotype and are associated with poor patient prognosis." (PMID 35267548, 2022). "Evidence shows that there is a state of chronic inflammation at tumor sites and that IL-4, particularly, is upregulated in the tumor microenvironment." (PMID 35606804, 2022). "IL4 signaling in macrophages controlled the expression of the chemokine receptor CXCR2, necessary for IL4-mediated tumor cell extravasation in vitro." (PMID 36077870, 2022). "On the other hand, Th2 cytokines like IL-4 as well as IL-13 can promote M2 polarization of macrophages, which exert anti-inflammatory, tumor promoting as well as parasite clearance effects." (PMID 35876627, 2022). "The salivary protein results showed that various inflammatory markers were higher in the saliva of tumor patients with a trend of increased IL-10, IL-4, and IL-8; MCP-1; TNF-α; and VEGF levels observed, probably linked with the disease." (PMID 34251535, 2022). "Type 1 T helper cells, which release TNF-a, IL-2, and interferon-g (IFN-g), exert antitumor effects, while Type 2 T helper cells mainly produce IL-4 to suppress the host immune system and promote tumor growth." (PMID 36171881, 2022). "Mast cells, through the release of IL-1, IL-4, and IL-6, are involved in the elimination of tumor cells and in the rejection of tumors." (PMID 36430483, 2022). "Anti-IL-25R treatment significantly reduced tumor number and size, and decreased IL-4 and IL-13 expressing tumor ILC2s." (PMID 35658010, 2022). "GM-CSF and IL-4 were added for in vitro induction, and tumor-bearing mice were induced to obtain MDSC-DCs." (PMID 36567953, 2022).